HIF1A (hypoxia inducible factor 1 subunit alpha)
Diseases named in the same sentence as HIF1A in open-access papers (continued):
Sharing a sentence is not in itself a finding about the gene and the disease.
osteosarcoma (continued). "HIF-1α and NUSAP1 were valuable targets for the treatment of osteosarcoma." (PMID 34322597, 2021). "In agreement with this hypothesis, several osteosarcoma cell lines present a high expression of ACAT, HIF1A, and VLDLR." (PMID 33178572, 2020). "Indeed, HIF-1α and VEGF-A knockdown decreased the invasive potential of Saos-2 and U2-OS osteosarcoma cell lines." (PMID 32085654, 2020). "Therefore, total RNA was prepared from osteosarcoma cell lines and the levels of AUF1 and HIF-1α mRNAs were measured by qRT-PCR." (PMID 31448053, 2019). "We found that HIF1A and HMGN5 were upregulated in osteosarcoma (OS) cells cultured in the hypoxic environment, and the results of overexpression and knockdown experiments showed that HIF1A upregulated the transcription factor GATA1 and further promoted the expression of HMGN5." (PMID 31930127, 2019). "Statistically, of the 17 osteosarcoma cases with elevated miR-199a, 14 (82.36%) of them had low levels of HIF-1α, and 25 of 28 (89.29%) cases with down-regulated miR-199a presented high levels of HIF-1α." (PMID 28442599, 2019). "Thus, HIF-1α silencing by siRNA reduces VEGF production by osteosarcoma cells in vitro and inhibits angiogenesis in a mouse model of osteosarcoma." (PMID 31370265, 2019). "Therefore, we plan to explore the relationship between HIF1A and HMGN5 in a hypoxic environment and its effect on osteosarcoma metastasis." (PMID 31930127, 2019). "Exposure to either HIF-1α siRNA, HIF-2α siRNA or HIF-1α plus HIF-2α siRNA suppressed secretion of ANGPTL4 under hypoxia, showing that ANGPTL4 is a target gene of both HIF-1α and HIF-2α in osteosarcoma cells." (PMID 29739381, 2018). "Therefore, WISP-1 induces VEGF-A expression and angiogenesis in osteosarcoma through the FAK, JNK and HIF-1α pathways." (PMID 28406476, 2017). "Similarly, TNFα induced nuclear buildup of a HIF-1α-eGFP chimera protein in the HIF-1α_U2OS Redistribution assay based on an osteosarcoma cell line." (PMID 22355351, 2012). "Similar results have been obtained in osteosarcoma cells, where TGF-β signaling induces a switch in the E-cadherin/N-cadherin cell profile as well as an increase in vimentin, whereas melatonin appears to reverse this effect through the inhibition of Snail, MMP-9 and HIF-1α." (PMID 38473317, 2024). "Interestingly, in contrast to classical chemotherapy, the dual SphK1 and S1P1 inhibitor FTY720 remarkably reduced cell proliferation to the same extent in normoxic and hypoxic conditions in all osteosarcoma cell lines, suggesting that efficacy of FTY720 was related to its anti-HIF-1α effect." (PMID 35158767, 2022). "In the human osteosarcoma cell line MG-63, a hypoxic environment (similar to that typically found in tumors) induces the expression of high amounts of SENP1, and inhibiting SENP1, in turn, reduces the expression of two major hypoxia-induced genes, HIF1α and VEGF (vascular endothelial growth factor)." (PMID 36078118, 2022). "The ability to reduce HIF1α levels provides a plausible mechanism for the anti-tumorigenic activity of HACE1, including potential roles in blocking metastasis, as it was recently shown that HACE1 overexpression completely eliminated detectable lung metastases of osteosarcoma cells in mice." (PMID 33603169, 2021). "Treating osteosarcoma cells with CCR5, FAK, AKT or HIF-1α inhibitors reversed CCL4-mediated inhibition of miR-3927-3p expression, which suggests that CCL4 may increase integrin αvβ3 expression and cell migration by inhibiting miR-3927-3p synthesis via CCR5 and FAK/AKT/HIF-1α signaling." (PMID 34884541, 2021). "It was interesting to find that HIF-1α is significantly up-regulated in cisplatin resistant cells at both protein and mRNA levels, intriguing us to explore the correlation of HIF-1α and miR-199a in the regulation of cisplatin sensitivities of osteosarcoma cells." (PMID 28442599, 2019).
osteosarcoma (continued). "However, in osteosarcoma cells, HIF-1α and HIF-2α expression levels were not obviously increased upon doxorubicin treatment, suggesting that HIF-mediated signaling is not evident in inducing CD47 upregulation in osteosarcoma and mechanisms that regulate CD47 expression can be tumor type-dependent." (PMID 36274066, 2022). "However, DEC2 knockdown effectively down-regulated HIF-1α protein levels in MNNG and 143B cell lines under normoxic conditions, and in all three cell lines under hypoxic conditions, indicating that in osteosarcoma cells DEC2 positively regulates HIF-1α at the post-transcriptional levels." (PMID 25884381, 2015). "Using Kaplan-Meier survival analysis, we found that high expression of HIF-1α was correlated with higher probability of metastasis and significantly reduced disease-free survival (DFS), suggesting that HIF-1 activation may be a determining factor for metastasis and EFS in osteosarcoma." (PMID 25884381, 2015). "In addition, when we cultured the cells under hypoxia, NO treatment led to no further stabilization of HIF-1α as HIF-1α levels were already very high, but also led to no degradation as observed for U2OS osteosarcoma cells." (PMID 34671319, 2021). "Whereas no HIF-1α protein in either U2OS or U2OS-M cells under normal culture conditions was observed, U2OS-M cells accumulated HIF-1α more rapidly than the parental U2OS cells after exposure to hypoxia, indicating the enhanced expression of DEC2 sensitizes osteosarcoma cells to hypoxia." (PMID 25884381, 2015).
colitis (141 papers, 2013 to 2026). Inflammation of the colon. "Myeloid HIF deficiency in DSS-induced colitis leads to increased infiltration of neutrophils and Ly6C monocytes, with a more marked impact from HIF-1α loss compared to HIF-2α." (PMID 38605960, 2024). "We have previously demonstrated in the context of acute colitis that loss of HIF-1α in NKp46+ cells prevents ILC3-to-ILC1 conversion, and confers protection against acute intestinal damage." (PMID 38876796, 2024). "Epithelial specific loss of HIF-1α results in a significantly more severe colitis then observed in wild-type animals." (PMID 36742292, 2023). "Conditional deletion of HIF1A leads to increased susceptibility to colitis in mice and has therefore been extensively linked to beneficial outcomes in murine models of colitis." (PMID 36614212, 2023). "In contrast, Von Hippel-Lindau (VHL)-deficient (i.e. Hif1α-stabilized) Treg cells favor Th1 differentiation over Treg differentiation, resulting in colitis development in adoptive T cell transfer model." (PMID 37809060, 2023). "HIF-1α-KO tTreg cells (Cd4CreHif1af/f) were as effective as Hif2af/f tTreg cells in suppressing colitis and associated pathologies in RAG-1-KO mice receiving effector T cells." (PMID 33024109, 2020). "In some other reports, HIF-1α induces Foxp3 and drives the generation and function of Tregs indicating that HIF-1α-deficient Tregs fail to control T-cell-mediated colitis." (PMID 33519819, 2020). "On the model of acute colitis in mice it was demonstrated that the deficiency of HIF-1α correlated with high mortality rates, and the surviving mice showed severe clinical manifestations of colitis." (PMID 31057785, 2019). "Mice deficient in myeloid HIF-1α showed reduced expression of IL-17 in our DSS-induced colitis model." (PMID 29261815, 2017). "Loss of myeloid HIF-1α resulted in a milder DSS-induced colitis with lower numbers of infiltrating immune cells." (PMID 29261815, 2017). "In contrast, increasing HIF-1α by pharmacological inhibition of its degradation substantially reduced the extent of injury caused by inflammatory damage in these colitis models." (PMID 27002817, 2016). "In summary, we demonstrated that cZFP609 was highly expressed in the CSMCs of Sirt1-Tg mice, which may be associated with increased susceptibility to colitis via suppression of HIF-1α nuclear translocation." (PMID 40076434, 2025). "Consequently, supplementation with acetyl-CoA improved defective IgA production in Hif1a-deficient B cells and limited experimental colitis." (PMID 39543372, 2025). "It is claimed that HIF-1α has been linked to myeloid cell function in DSS-induced colitis." (PMID 36768744, 2023). "Therefore, myeloid hypoxia-induced HIF-1α causes IL-17 secretion to elevate, which, in turn, causes severe colon inflammation in mice with high levels of pro-inflammatory cytokines." (PMID 36768744, 2023). "However, further studies are essential for the understanding of the possible protective role of increased expression of HIF-1α in susceptible-to-hypoxia animals on a colitis model." (PMID 31057785, 2019). "Therefore, we used 2.5% DSS-induced colitis model to address the consequences of IEC- derived Hif-1α deficiency for intestinal physiology." (PMID 31040849, 2019). "We hereby report that HIF-1α in myeloid cells critically regulates the susceptibility towards DSS-induced colitis, indicating that HIF-1α in myeloid cells could become a novel therapeutic target to treat the disease." (PMID 29967068, 2018). "Mice with loss of myeloid HIF-1α showed an overall milder disease outcome of DSS-induced colitis." (PMID 29261815, 2017). "In addition, we revealed that the loss of function of the HIF-1α/TFF-3 axis in DSS-induced colitis in mice may promote intestinal barrier dysfunction." (PMID 32713852, 2020).
colitis (continued). "Although myeloid HIF-1α has been recently implicated in promoting DSS-induced colitis, we hypothesize that these disparate results are likely due to different phases of inflammation under examination, and/or different effects of the gene promoters driving Cre-mediated recombination." (PMID 30455703, 2018). "A recent study has demonstrated that activation of HIF-1α in colonic myeloid cells can accelerate the progression of colitis." (PMID 41378888, 2026). "Berberine reduces HIF-1α levels by 40% in colonic tissue of DSS-induced colitis mice by downregulating the TLR4/NF-κB/HIF-1α axis, concurrently decreasing TNF-α and IL-6 secretion and alleviating inflammatory infiltration." (PMID 41480384, 2025). "In summary, these findings demonstrate that L. paracaseiL21 and its postbiotic mitigate colitis by enhancing SCFA-mediated activation of AhR/HIF1α signaling, thereby promoting IL-22-dependent mucin synthesis and goblet cell regeneration." (PMID 40806121, 2025). "In a previous study, this medication was shown to modulate colitis and dose-dependently inhibit serum levels of inflammatory cytokines by regulating the inflammation-associated pathways Ras-PI3K-Akt-HIF-1α and NF-κB." (PMID 40283919, 2025). "Together, these data indicate that GTA treatment in vivo protects against the aggravated colitis phenotype of Hif1a cKO mice, most likely through enhanced IgA-producing B-cell differentiation." (PMID 39543372, 2025). "The study discovered that the intervention of L. paracaseiL21 resulted in a significant increase in the content of SCFAs and the levels of AhR and HIF1α in the colon of mice with DSS-induced colitis, leading to an upregulation of IL-22 production." (PMID 40806121, 2025). "We show that Sirt1-Tg mice have more secretion of cZFP609 in DSS-induced mouse colitis, thus, they detained HIF-1α in the cytoplasm." (PMID 40076434, 2025). "Given that mucosal IgA plays a crucial role in colon homeostasis, we characterized Hif1a cKO mice subjected to DSS-induced colitis." (PMID 39543372, 2025). "L. paracaseiL21 and its heat-inactivated postbiotic mitigated DSS colitis similarly attenuated DSS-colitis by modulating the NF-κB and HIF1α/AhR-IL-22-MUC2 axes." (PMID 40806121, 2025). "Similarly, it was also shown that spermidine, a natural polyamine, could enhance oxidative phosphorylation and FAO processes through activation of the AMPK/HIF-1α pathway, causing macrophages to exhibit anti-inflammatory properties, ultimately effectively ameliorating colitis in mice." (PMID 40243444, 2025). "Loss of HIF-1α in B cells affects IgA-producing B-cell differentiation and exacerbates dextran sodium sulfate (DSS)-induced colitis." (PMID 39543372, 2025). "Our findings shed light on the crucial metabolic influence of HIF-1α on the IgA response in controlling intestinal inflammation during DSS-induced colitis." (PMID 39543372, 2025). "Next, we compared the microbiota composition in the guts of WT mice and Hif1a cKO mice treated with vehicle or RXD during DSS-induced colitis." (PMID 39543372, 2025). "Recent studies have shown that regulating glycolysis and M1 polarization facilitate the recovery from colitis by inhibiting the mTORC1/HIF-1α signaling pathway; this therapeutic effect can be counteracted by the mTORC1 agonist, l-leucine." (PMID 41030455, 2025). "Intracellular HIF-1α activation was also proved to effectively facilitate the progression of colitis." (PMID 40691131, 2025). "The results showed that, compared to the DSS‐induced colitis model group, EcN‐T treatment significantly downregulated the expression of HIF‐1α, GLUT1, and PFKFB3, which was consistent with the results of the volcano plot analysis." (PMID 41244343, 2025). "Myeloid HIF-1α deficits encourage pro-inflammatory neutrophil and monocyte infiltration, hinder M2 polarization, and worsen colitis." (PMID 38605960, 2024).
colitis (continued). "In mouse IEC, butyrate eases DSS-induced colitis by upregulating HIF-1α to modulate autophagy and gut microbiota; however, HIF-1α deficiency lowers intestinal butyrate concentration and autophagy levels to increase susceptibility to colitis." (PMID 38605960, 2024). "Mesenchymal stem cells, for example, encourage an anti-inflammatory state by shifting macrophages from M1 to M2 phenotypes through HIF-1α pathways, easing colitis." (PMID 38605960, 2024). "Ellagic acid and ellagitannins are polyphenolics that induce the expression of miR-145 and attenuate colitis via miR-145/p70S6K/HIF1α axis." (PMID 39457040, 2024). "Adaptation to low oxygen is mediated by hypoxia-inducible transcription factors (HIFs), and the HIF-1α subunit shapes an ILC phenotype upon acute colitis that contributes to intestinal damage." (PMID 38876796, 2024). "For instance, HIF-1α–dependent induction of FoxP3 enhanced anti-inflammatory effect of regulatory T cells and protected against T-cell–mediated colitis." (PMID 39585307, 2024). "For example, moderate hypoxia preserves the intestinal barrier in mouse dextran sulfate sodium (DSS)-induced colitis via HIF-1α modulation of Vitamin D Receptor (VDR) signaling." (PMID 38605960, 2024). "Taken together, our results identify HIF-1α in NKp46+ cells as a double-edged sword and a critical nexus that orchestrates type 1 inflammation during acute colitis versus profibrotic responses in the context of chronic colitis." (PMID 38876796, 2024). "ILC1 activation by the oxygen-sensitive transcription factor HIF-1α is detrimental upon acute colitis, but protects against inflammation and fibrosis during chronic colitis." (PMID 38876796, 2024). "DPCA's ability to protect against DSS‐induced colitis is likely a direct effect of HIF‐1α stabilization in the colon, which serves to increase mucus production and the expression of barrier‐protective genes." (PMID 38247203, 2024). "Of note, while both prolyl hydroxylase (PHD) and von Hipple Lindau inhibition result in HIF activation, PHD inhibitors or genetic disruption of PHDs have been shown to effectively activate HIF-1α and to improve gut barrier function in murine colitis models." (PMID 39585307, 2024). "In DSS-induced colitis mice, myeloid HIF-1α deletion lessened inflammation, HIF-2α deletion worsened it, and the absence of both showed no significant changes; however, increased myeloid expression of HIF-1α accelerated colitis progression." (PMID 38605960, 2024). "Butyrate suppresses HDAC and activates the p-glycogen synthase kinase-3β (GSK-3β)/β-catenin/HIF-1α/NF-κB pathway, reducing inflammation in sleep deprivation-induced colitis mice." (PMID 38605960, 2024). "It is thus possible that the inflammatory response during colitis-induced FGF21 expression inhibits intestinal HIF1α expression, leading to a decrease in IL-22 and therefore exacerbating the expression of inflammatory IL-6 production." (PMID 37432218, 2023). "In the TNBS colitis prevention trial, Hif1a and Tgfb1 expression was elevated by MTADV as in the therapeutic trial, but it also caused an increase in Tnfa, Vegfa, and Il10." (PMID 37047397, 2023). "In the gut, HIF-1α-driven expression of IL-33 can enhance inflammation in mice with dextran sulfate sodium (DSS)-induced colitis." (PMID 37375100, 2023). "In both situations, increased stabilization of HIF-1α results in increased barrier function in the context of colitis." (PMID 36742292, 2023). "At that, in a dextran sodium sulfate (DSS) model of colitis, administration of butyrate facilitated colon damage and suppressed inflammation in Cre-/HIF-1α- mice." (PMID 36768744, 2023). "Meanwhile, in the pathogenesis of colitis with depletion of epithelial O2, changes in colonic HIF-1α expression are related to barrier permeability through the claudin-1 pathway." (PMID 37509556, 2023). "In the setting of colitis, HIF-1α has been shown to be essential for regulating the inflammatory process." (PMID 36742292, 2023).